ENSG00000260537 (novel protein, DDX19B and DDX19A readthrough)
Gene: Protein-coding gene on chromosome 16 (70,299,194 to 70,372,582, forward strand). Ensembl gene ENSG00000260537.
Genetic constraint (gnomAD): Loss-of-function variants: 13 observed, 51.99 expected, observed/expected ratio (o/e) 0.25, 90% interval 0.16 to 0.4. Missense variants: 298 observed, 562.26 expected, observed/expected ratio (o/e) 0.53, 90% interval 0.48 to 0.58. Synonymous variants: 200 observed, 205.55 expected, observed/expected ratio (o/e) 0.97, 90% interval 0.87 to 1.09.